KCTD16 (potassium channel tetramerization domain containing 16)
Description:
Auxiliary subunit of GABA-B receptors that determine the pharmacology and kinetics of the receptor response. Increases agonist potency and markedly alter the G protein signaling of the receptors by accelerating onset and promoting desensitization (By similarity).
Synonyms: KIAA1317
Tractability: Antibody: UniProt places it where antibodies can reach, with medium confidence; its Gene Ontology location is reachable by antibodies, with medium confidence. PROTAC: ubiquitination databases record sites on it; its protein half-life has been measured.
Gene: Protein-coding gene on chromosome 5 (144,170,873 to 144,485,686, forward strand). Ensembl gene ENSG00000183775.
Subcellular location: Presynaptic cell membrane; Postsynaptic cell membrane
Subcellular location (Human Protein Atlas): Centrosome; End piece; Mid piece; Principal piece; Vesicles
Gene Ontology:
Molecular function: protein binding; identical protein binding
Biological process: nervous system development; regulation of G protein-coupled receptor signaling pathway; protein homooligomerization
Cellular component: postsynaptic membrane; presynaptic active zone membrane; receptor complex; presynaptic membrane
Genetic constraint (gnomAD): Loss-of-function variants: 10 observed, 31.6 expected, observed/expected ratio (o/e) 0.32, 90% interval 0.19 to 0.54. The upper end of that interval is the gene's LOEUF score, 0.54, which puts it in group 2 of 6, group 1 being the genes least tolerant of losing a copy. Missense variants: 438 observed, 545.3 expected, observed/expected ratio (o/e) 0.8, 90% interval 0.74 to 0.87. Synonymous variants: 194 observed, 203.29 expected, observed/expected ratio (o/e) 0.95, 90% interval 0.85 to 1.08.
Homologues: Orthologues: chimpanzee KCTD16 (100% identical), rabbit KCTD16 (98% identical), dog KCTD16 (98% identical), pig KCTD16 (97% identical), guinea pig KCTD16 (97% identical), mouse Kctd16 (96% identical), rat Kctd16 (96% identical), tropical clawed frog kctd16 (86% identical), zebrafish kctd16b (75% identical), macaque KCTD16 (66% identical), zebrafish kctd16a (43% identical), Caenorhabditis elegans F32B4.5 (16% identical), and 1 more. Paralogues in human: KCTD8 (62% identical), KCTD12 (39% identical), KCTD19 (18% identical), KCTD18 (17% identical), KCTD1 (16% identical), KCTD15 (15% identical), KCNRG (14% identical), KCTD14 (14% identical), KCTD21 (14% identical), KCTD7 (14% identical), KCTD6 (13% identical), KCTD11 (12% identical), and 1 more.
Diseases named in the same sentence as KCTD16 in open-access papers:
KCTD16 is named in the same sentence as 12 diseases in open-access papers, as found by Europe PMC text mining. Sharing a sentence is not in itself a finding about the gene and the disease. The quoted sentences say what the papers report.
lung carcinoma (2 papers, 2021 to 2022). "Additionally, KCTD16 antibodies were identified in 72% of patients with anti-GABABR encephalitis, using in-house IIFA on cells transfected only with KCTD16, and their presence indicated a higher association with lung cancer." (PMID 34267758, 2021).
small cell lung carcinoma (2 papers, 2021 to 2025). Small cell lung cancer (SCLC) is a highly aggressive malignant neoplasm, accounting for 10-15% of lung cancer cases, characterized byrapid growth, and early metastasis. "KCTD16 is a transcriptional target of ASCL1, one of the master transcription factors of small cell lung carcinoma, (SCLC)." (PMID 34001146, 2021).
epilepsy (1 paper, 2019). A brain disorder characterized by episodes of abnormally increased neuronal discharge resulting in transient episodes of sensory or motor neurological dysfunction, or psychic dysfunction. "Interestingly, a KCTD16 polymorphism has been associated with epilepsy by a genetic linkage study." (PMID 30736458, 2019).
Sensorimotor neuropathy (1 paper, 2023). "These include entities such as KCTD16 (associated with limbic encephalitis), neuronal intermediate filament (associated with cerebellar syndrome) and ANNA-3 (associated with sensorimotor neuropathy and cerebellar syndrome)." (PMID 37606434, 2023).
thyroid cancer (1 paper, 2019). "KCTD16 has been found to be associated with thyroid cancer, while KCTD12, a member of the KCTD family, has been found to be associated with uveal melanoma." (PMID 31146393, 2019).
tumor (5 papers, 2021 to 2026). "The CNVs in C1 were mainly associated with tumor cell proliferation, such as the amplification of 5q31.3 (KCTD16) and 7p22.2 (SDK1), as well as the deletion of 4q24 (PPA2)." (PMID 34804944, 2021). "Tumor cells express GABAB receptors or related antigens, such as KCTD16, triggering antibody production through molecular mimicry." (PMID 41235243, 2025).
cancer (2 papers, 2025). A tumor composed of atypical neoplastic, often pleomorphic cells that invade other tissues. "Emerging evidence has highlighted the significance of various gene families in cancer progression, including the KCTD family, comprising genes, including KCTD2, KCTD5, KCTD9, KCTD10, KCTD12, KCTD15, KCTD16, and KCTD21." (PMID 40832836, 2025).
KCTD16 also shares sentences with these, for which no sentence is quoted: adenocarcinoma (1 paper); encephalitis (1); genetic disease (1); medulloblastoma (1); uveal melanoma (1).